MYH14 (myosin heavy chain 14)
Description:
Cellular myosin that appears to play a role in cytokinesis, cell shape, and specialized functions such as secretion and capping.
Synonyms: NMHC II-C; KIAA2034; FP17425; FLJ13881; MHC16; MYH17; DFNA4; DFNA4A; NMHC-II-C; PNMHH; myosin
Tractability: Small molecule: a structure with a bound ligand is known. PROTAC: ubiquitination databases record sites on it; its protein half-life has been measured; a small molecule that binds it is known.
Gene: Protein-coding gene on chromosome 19 (50,188,186 to 50,310,545, forward strand). Ensembl gene ENSG00000105357.
Subcellular location (Human Protein Atlas): Nucleoplasm
Pathways (Reactome):
Signal Transduction: RHO GTPases Activate ROCKs; RHO GTPases activate CIT; RHO GTPases activate PAKs; RHO GTPases activate PKNs
Developmental Biology: EPHA-mediated growth cone collapse; Sema4D induced cell migration and growth-cone collapse
Gene Ontology:
Molecular function: actin filament binding; microfilament motor activity; ATP binding; cytoskeletal motor activity
Biological process: actomyosin structure organization; mitochondrion organization; neuronal action potential; sensory perception of sound; skeletal muscle contraction; skeletal muscle tissue development; vocalization behavior; mitotic cytokinesis; regulation of cell shape
Cellular component: actomyosin; extracellular exosome; membrane; myosin II complex; myosin II filament; cytoplasm; cytosol; myosin filament; axon; brush border; growth cone; myosin complex; stress fiber; supramolecular fiber
Genetic constraint (gnomAD): Loss-of-function variants: 118 observed, 212.5 expected, observed/expected ratio (o/e) 0.56, 90% interval 0.48 to 0.65. The upper end of that interval is the gene's LOEUF score, 0.65, which puts it in group 2 of 6, group 1 being the genes least tolerant of losing a copy. Missense variants: 2,402 observed, 2,604.9 expected, observed/expected ratio (o/e) 0.92, 90% interval 0.89 to 0.95. Synonymous variants: 1,089 observed, 1,068.7 expected, observed/expected ratio (o/e) 1.02, 90% interval 0.97 to 1.07.
Gene-disease validity (ClinGen):
ClinGen rates the evidence that MYH14 causes each of these diseases.
nonsyndromic genetic hearing loss (autosomal dominant): Moderate. A disease characterized by hearing loss that is not part of a larger syndrome.
Homologues: Orthologues: chimpanzee MYH14 (99% identical), macaque MYH14 (99% identical), pig MYH14 (95% identical), rat Myh14 (93% identical), mouse Myh14 (92% identical), dog MYH14 (92% identical), guinea pig MYH14 (92% identical), tropical clawed frog myh14 (69% identical), zebrafish myh14 (62% identical). Paralogues in human: MYH10 (65% identical), MYH9 (62% identical), MYH11 (61% identical), MYH7B (38% identical), MYH3 (37% identical), MYH7 (37% identical), MYH2 (37% identical), MYH6 (37% identical), MYH8 (37% identical), MYH1 (36% identical), MYH4 (36% identical), MYH13 (36% identical), and 32 more.